CEBPB (CCAAT enhancer binding protein beta)
Diseases named in the same sentence as CEBPB in open-access papers (continued):
Sharing a sentence is not in itself a finding about the gene and the disease.
lung adenocarcinoma (4 papers, 2015 to 2024). A carcinoma that arises from the lung and is characterized by the presence of malignant glandular epithelial cells. "We then used a public integrative database (cBioPortal) to analyze the correlation of the expression of CEBPB with that of CCL28 in 44 lung adenocarcinoma cell lines." (PMID 39075504, 2024). "The CEBPB promoters were unmethylated in all lung adenocarcinoma samples with available methylation data (n = 185), whereas the CEBPA promoter regions were frequently aberrantly methylated, consistent with previous results." (PMID 25767874, 2015). "Our study showed that after undergoing anti-angiogenesis treatment, the tumor exhibited a state of ischemia and hypoxia, leading to an upregulation in the expression of CCL28 in hypoxic lung adenocarcinoma cells by the hypoxia-sensitive transcription factor CEBPB." (PMID 39075504, 2024). "In addition, disease-free survival and overall survival of lung adenocarcinoma patients with high CEBPB expression were significantly decreased (p = 0.0065 and p = 0.032, respectively)." (PMID 39075504, 2024). "HIF1A expression was correlated with CEBPB and SLC2A1 in lung adenocarcinoma." (PMID 39858431, 2024). "Analyses of data from The Cancer Genome Atlas (TCGA) revealed that expression, promoter methylation, or copy number of CEBPB was not significantly altered in human lung adenocarcinoma." (PMID 25767874, 2015).
malignant glioma (4 papers, 2014 to 2026). A grade III or grade IV glioma arising from the central nervous system. "CEBPB can bind to the promoter region of TDO2, and the two are highly enriched in mesenchymal subtypes of malignant gliomas, which are associated with a poor prognosis." (PMID 38887298, 2024). "Likewise, CEBPB was significantly upregulated in malignant gliomas, especially in the mesenchymal subtype." (PMID 41436600, 2026).
multiple sclerosis (4 papers, 2017 to 2025). A progressive autoimmune disorder affecting the central nervous system resulting in demyelination. "CEBPB is a transcription factor that plays diverse roles in inflammation, e.g., through T helper cell 17 (TH17)-dependent regulation of inflammation in models of multiple sclerosis." (PMID 32325790, 2020).
osteoporosis (4 papers, 2022 to 2026). A condition of reduced bone mass, with decreased cortical thickness and a decrease in the number and size of the trabeculae of cancellous bone (but normal chemical composition), resulting in increased fracture incidence. "The shared presence of CEBPB, CTCF, and TCF12 in the regulatory networks of both BRP and OSP genes suggests their potential involvement in the underlying mechanisms of both bone regeneration and osteoporosis." (PMID 37875547, 2023). "Altered CEBPB activity may contribute to the development or progression of osteoporosis." (PMID 37875547, 2023). "The shared TFs CEBPB, CTCF, and TCF12 in the OSP and BRP genes indicate their potential dual role in bone formation and remodeling, suggesting their involvement in osteoporosis." (PMID 37875547, 2023). "Further work will focus on the exact contribution of NFIC, BACH1, CEBPB, and POU2F2 to osteoporosis pathogenesis." (PMID 35757392, 2022). "The core transcription factors in the ceRNA network, NFIC, BACH1, CEBPB, and POU2F2, might be related to osteoporosis." (PMID 35757392, 2022).
preeclampsia (4 papers, 2016 to 2024). Preeclampsia is a hypertensive disorder of pregnancy that is characterized by new-onset hypertension with proteinuria presenting after 20 weeks of gestation, and depending on mild or severe forms may initially present with severe headache, visual disturbances, and hyperreflexia. "This is especially important in the clinical context, as CEBPB was recently reported to be involved in EVT dysfunction in the severe preeclampsia placenta." (PMID 38267607, 2024). "For the first time, the transcriptional factors CEBPB and GTF2B were described, and their involvement in EVTs dysfunction in preeclampsia was reported." (PMID 36981026, 2023). "After further in vitro cell experiments, it was found that CEBPB and GTF2B can regulate cell apoptosis and invasion, which may be involved in the preeclampsia pathological processes." (PMID 36981026, 2023).
tuberculosis (4 papers, 2014 to 2024). A chronic, recurrent infection caused by the bacterium Mycobacterium tuberculosis. "This suggests that in Mtb-infected AEC-II cells, the ERK1/2 pathway mediates the phosphorylation of CEBPB, thereby upregulating hBD1 expression to exert its anti-tuberculosis effect." (PMID 38397085, 2024). "In macrophages, the AMPK-PPARGC1A pathway involving CEBPB upregulates multiple autophagy-related genes, promoting autophagy activation and exerting anti-tuberculosis effects." (PMID 38397085, 2024). "Through a literature review, we found that the transcriptional activity of CEBPB can be regulated by various signaling pathways, including MAPK and NF-κB, which are important in the regulation of anti-tuberculosis immune response." (PMID 38397085, 2024). "In summary, our study demonstrated that increased hBD1 expression during Mtb infection can inhibit the survival of Mtb, and CEBPB can be phosphorylated by ERK1/2, effectively promoting hBD1 expression and exerting anti-tuberculosis effects." (PMID 38397085, 2024). "Considering the consistency between CEBPB and DEFB1 expression, we hypothesized that promoting AMP expression might be one of the ways in which CEBPB exerts its anti-tuberculosis immune effects." (PMID 38397085, 2024). "However, the approach of CEBPB taking part in anti-tuberculosis immunity in AEC-II cells has not been reported." (PMID 38397085, 2024). "In summary, we found that upregulation of hBD1 in AEC-II cells is mediated by CEBPB activated by ERK1/2 following Mtb infection, but not by STAT1, and promotes anti-tuberculosis effect." (PMID 38397085, 2024).
ulcerative colitis (4 papers, 2024 to 2025). An inflammatory bowel disease involving the mucosal surface of the large intestine and rectum. "SLC6A14 negatively regulates PAK6 in a manner dependent on CCAAT enhancer binding protein beta (C/EBPβ), promoting epithelial cell ferroptosis in ulcerative colitis via the C/EBPβ–PAK6 axis." (PMID 39218897, 2024).
autoimmune disease (3 papers, 2022). A disorder resulting from loss of function or tissue destruction of an organ or multiple organs, arising from humoral or cellular immune responses of the individual to their own tissue constituents. "It has been extensively reported that CEBPB participates in immune regulation, and CEBPB contributes to immune activation in many scenarios and relates to the occurrence of many autoimmune diseases." (PMID 36353635, 2022). "CEBPD is a transcription factor that forms a heterodimer with CEBPB (PPi score = 0.991), which further regulates the transcription of IL-6, a key proinflammatory cytokine overexpressed in multiple autoimmune diseases." (PMID 35627163, 2022).
bladder cancer (3 papers, 2018 to 2024). "At the same time, there are also studies reporting that CEBPB plays a pro-cancer role in bladder cancer." (PMID 38710698, 2024). "CEBPB is involved in the transcriptional regulation of LncRNA UCA1, promoting its high expression and thereby promoting the proliferation of bladder cancer cells." (PMID 38710698, 2024).
cholangiocarcinoma (3 papers, 2019 to 2023). A carcinoma that arises from the intrahepatic biliary tree (intrahepatic cholangiocarcinoma) or from the junction, or adjacent to the junction, of the right and left hepatic ducts (hilar cholangiocarcinoma). "Additionally, CEBPB was identified as a substrate of m6A modification in autoimmune conditions and cholangiocarcinoma." (PMID 37229206, 2023).
experimental autoimmune encephalomyelitis (3 papers, 2017 to 2025). An autoimmune demyelinating disease of the central nervous system that is produced experimentally in animals by the injection of homogenized brain or spinal cord in Freund's adjuvant. "It is a key driver of experimental autoimmune encephalomyelitis (EAE) autoimmune inflammation, and infiltration of lymphocytes and antigen-presenting cells into the central nervous system decreased in CEBPB-/- mice after EAE induction." (PMID 35204186, 2022).
female infertility (3 papers, 2017 to 2022). Diminished or absent ability of a female to achieve conception. "Specifically, VDR is associated with female infertility, whereas CEBPB has been described as relevant factor for female reproduction for its role in ovarian follicle development, together with SMAD3 and ESR2." (PMID 36589743, 2022). "Finally, female infertility has been implicated in transcription factor CEBPB deficient animals." (PMID 35899878, 2022).
liposarcoma (3 papers, 2008 to 2022). A usually painless malignant tumor that arises from adipose tissue. "Although CEBPB and CEBPD are expressed early in adipogenesis and promote PPARG2 mRNA expression, induction of either gene is insufficient to drive PPARG2 mRNA upregulation in the liposarcoma tissues in the absence of ZFP423 protein." (PMID 35313831, 2022).
oral cancer (3 papers, 2014 to 2017). "Importantly, Akt notably enhanced the CCAAT/enhancer binding protein (C/EBP) β (C/EBPβ; CEBPB), as evidenced by the increased expression of C/EBPβ after Akt activation in oral cancer cells." (PMID 28708091, 2017).
papilloma (3 papers, 2019 to 2023). A benign epithelial neoplasm that projects above the surrounding epithelial surface and consists of villous or arborescent outgrowths of fibrovascular stroma. "For example, CEBPB−/− mice are completely resistant to papilloma induced by chemical carcinogens, which was in accord with our report that silencing of CEBPB can increase ASS1 expression and alleviate the malignant biological behaviors and tumor progression." (PMID 35674458, 2022).
adenomyosis (2 papers, 2019 to 2023). The growth of endometrial tissue inside the muscular wall of the uterine corpus. "We also found that the increased expression and DNA hypomethylation of CEBPB were associated with adenomyosis." (PMID 31576674, 2019). "This study is the first to report the relationship between adenomyosis and the aberrant CEBPB expression and methylation and provides an important basis for further mechanistic studies on adenomyosis." (PMID 31576674, 2019). "We will further study the detailed role of CEBPB in the pathogenesis of adenomyosis." (PMID 31576674, 2019). "An amplicon including 18 CpG sites (nine units) in CEBPB (−588 bp to −45 bp, relative to transcription start site) was analysed in 10 normal endometrium and 10 paired eutopic and ectopic endometrium from women with adenomyosis using the MassARRAY system (Sequenom)." (PMID 31576674, 2019).
Burkitt lymphoma (2 papers, 2022 to 2024). A rare form of malignant mature B-cell non-Hodgkin lymphoma. "Similarly, STAT3 and CEBPB in SNB19 cell line, CHAF1A in IMR32 cell line, and BCL6 in Burkitt lymphoma cell line were identified by RegEnrich, with the GSEA method, as one of the top 20 key regulators in each corresponding dataset." (PMID 35017649, 2022).
colon adenocarcinoma (2 papers, 2025). "It has been shown that colon adenocarcinoma cells displayed reduced tumorigenic potential when transplanted into CEBPB-deficient animals." (PMID 40226120, 2025).
Ewing sarcoma (2 papers, 2017 to 2025). A small round cell tumor that lacks morphologic, immunohistochemical, and electron microscopic evidence of neuroectodermal differentiation. "As a transcriptional target of EWS-FLI1, the causative translocation of the majority of Ewing tumors, CEBPB is likely up-regulated in many cases of Ewing sarcoma." (PMID 28148901, 2017). "We employed gene knockdown and rescue assays to explore the consequences of altered CEBPB gene expression in Ewing sarcoma cell lines." (PMID 28148901, 2017). "CEBPB copy number gain in Ewing sarcoma was previously shown to be associated with worse clinical outcome compared to tumors with normal CEBPB copy number, although the mechanism was not characterized." (PMID 28148901, 2017). "In summary, we have identified CEBPB as an oncogene in Ewing sarcoma." (PMID 28148901, 2017). "Immunohistochemical staining showed increased C/EBPβ nuclear staining in this and other Ewing sarcoma samples with CEBPB gain compared to other Ewing sarcoma tumors and non-tumor controls with normal CEBPB copy number." (PMID 28148901, 2017).
influenza (2 papers, 2013 to 2024). An acute viral infection of the respiratory tract, occurring in isolated cases, in epidemics, or in pandemics; it is caused by serologically different strains of viruses (influenzaviruses) designated A, B, and C, has a 3-day incubation period, and usually lasts for 3 to 10 days. "For instance, hsa-miR-6890-5p, CEBPB, Cyclosporine, Influenza, and RBM39 have interactive relationships centered around OAS1." (PMID 38601162, 2024).
monocytic leukemia (2 papers, 2018 to 2025). "In French–American–British (FAB) acute myelomonocytic/monoblastic and monocytic leukemia cells, a high CEBPB level promotes monocytic differentiation." (PMID 40874179, 2025).
myocarditis (2 papers, 2022 to 2025). Myocarditis is a condition that is characterized by inflammation of the heart muscle (myocardium). "In this study, we figured out CEBPB as a major transcription factor and the key regulator of fatty acid metabolism in classical monocytes during BNT162b2-myocarditis." (PMID 36225942, 2022). "Also, we confirmed not only PDK4, but also CPT1A and ACSL1, which are known to be key regulators of fatty acid metabolism, are the target transcripts of CEBPB in classical monocytes in BNT162b2-myocarditis." (PMID 36225942, 2022).
nephritis (2 papers, 2023 to 2025). Inflammation of renal tissue. "Downregulation of CEBPB alleviated the autoimmune response and the development of nephritis in LN mice." (PMID 37828427, 2023).
neuropathy (2 papers, 2022 to 2024). A disorder affecting the nervous system that manifests with pain, tingling, numbness, and/or muscle weakness. "Specific genes increased in patients withoutlinezolid-associated neuropathy included ATG4C, BAX, and IGF1, while patients onlinezolid who suffered from neuropathy had an increase in AURKB, CASP3, CASP8, CDK1,CDKN1B, CEBPB, NADSYN1, NRF1, GPX7, and SBSN." (PMID 38939039, 2024).
neutropenia (2 papers, 2011 to 2024). A decrease in the number of neutrophils found in the blood. "We also demonstrated that missense mutations in exon 3 of ELANE induce neutropenia that can be ameliorated by G-CSF through alternative activation of CEBPB-dependent granulopoiesis, as shown in primary myelopoiesis from patients." (PMID 39560992, 2024).
oral candidiasis (2 papers, 2015 to 2024). Infection of the mucosal lining of the mouth with the fungus Candida albicans. "Other studies showed that CEBPB−/− mice were found to be resistant to oral candidiasis, showing increased susceptibility only under conditions of steroid-induced immunosuppression." (PMID 38750508, 2024).
Ovarian tumors (2 papers, 2018 to 2025). "Our analysis of human ovarian tumors indicated a higher probability of platinum resistance in patients exhibiting high levels of CEBPB mRNA (TCGA dataset) or C/EBPβ protein (IHC analysis)." (PMID 29712898, 2018).
periodontitis (2 papers, 2022 to 2023). An acute or chronic inflammatory process that affects the tissues that surround and support the teeth. "We believe that CEBPB also plays an important role in periodontitis-related immune responses." (PMID 35901060, 2022). "In contrast, 8 MRs (ESR1, CEBPB, FOS, BCL6, E2F1, SPI1, STAT3, and ETS1) were consistently expressed at higher levels (U test statistic between 10 and 16) in the periodontitis condition." (PMID 37834287, 2023).
sarcopenia (2 papers, 2018 to 2024). Progressive decline in muscle mass due to aging which results in decreased functional capacity of muscles. "Specifically, in the sarcopenia dataset, the CEBPB showed the best diagnostic efficiency for differentiating sarcopenia, while BTG2, CDKN1A, CEBPB, DDIT4, and NFKBIA showed the best-differentiating capability in the OA dataset." (PMID 38962732, 2024). "In the sarcopenia dataset, BTG2 (AUC = 0.867), CDKN1A (AUC = 0.892), CEBPB (AUC = 0.942), DDIT4 (AUC = 0.792), FOXO3 (AUC = 0.900), NFKBIA (AUC = 0.892), ZBTB16 (AUC = 0.808) and ZFP36 (AUC = 0.775) demonstrated better diagnostic efficacy in distinguishing sarcopenia patients from healthy controls." (PMID 38962732, 2024).
Stroke (2 papers, 2013 to 2014). Sudden impairment of blood flow to a part of the brain due to occlusion or rupture of an artery to the brain. "CEBPB is also enriched in astrocytes, relative to neurons and oligodendrocytes, and has been found to be up-regulated in reactive astrocytes responding to stroke or LPS." (PMID 25187168, 2014).
acne (1 paper, 2024). An inflammatory process of the sebaceous glands which is characterized by comedones, nodules, papules and/or pustules on the skin. "The expression of CXCL10, MMP9, IL1B, CXCL8, and CXCR4 were co-regulated by IRF1, STAT1, STAT3, IKBKB, HDAC1, ETS1, and CEBPB, which were highly expressed in rosacea and acne lesions." (PMID 38321132, 2024).
acute leukemia (1 paper, 2014). A clonal (malignant) hematopoietic disorder with an acute onset, affecting the bone marrow and the peripheral blood. "Several (i.e. CEBPB, FOS and FOSB) were also described to be deregulated in the transition of CML blastic phase to an acute leukemia." (PMID 24517546, 2014).
age (1 paper, 2015). A temporal measurement of the time period elapsed since an identifiable point in the life cycle of an organism. "Thus, in a microcosm, we intended to create a model to assess the relevance of chronic circulating CEBPB expression that in future research could be applied to the study of age-related functional impairment." (PMID 25391587, 2015).
alcoholic hepatitis (1 paper, 2019). Acute hepatitis resulting from ingestion of alcohol. "To investigate the clinical relevance of our findings, we examined the protein levels of Nogo-B, CD36, CEBPβ, and p-YAP by western blot analysis in 16 pairs of human NAFLD-associated HCCs without either viral or alcoholic hepatitis, and 12 pairs of HBV-positive HCC patients." (PMID 31358770, 2019).
aneurysm (1 paper, 2024). Bulging or ballooning in an area of an artery secondary to arterial wall weakening. "Therefore, CEBPB may serve as a diagnostic signature for aneurysm rupture and a potential target for intervention." (PMID 38332649, 2024). "After screening and validation, it was finally determined that CEBPB may be the hub gene for aneurysm rupture." (PMID 38332649, 2024).
benign ovarian tumor (1 paper, 2021). "We examined CEBPB and LOC102724169 expression among human EOC tumor tissues and benign ovarian tumor (BOT) tissues and found that both had lower expression in EOC patients." (PMID 33850634, 2021).
bile duct cancer (1 paper, 2023). "Future study to address the efficacy of FGFR2 and CEBPB as neo-biomarkers for cancer risk stratification of CC patients and drug targets for bile duct cancer treatment in a larger patient cohort with long-term follow up is warranted." (PMID 36996081, 2023). "A long-term follow up of this subgroup of CC patients is needed to confirm if elevated expression of CEBPB and FGFR2 is associated with the higher incidence of bile duct cancer in these patients." (PMID 36996081, 2023).
brucellosis (1 paper, 2024). Brucellosis is a bacterial infection that spreads from animals to people via unpasteurized dairy products or by exposure to contaminated animal products or infected animals. "As the major contributor of potential inflammatory storm, many inflammatory response genes (e.g., ITGB2, OSM, FPR1, CEBPB, NINJ1) and canonical pro‐inflammatory cytokines (e.g., CXCL8, CCL3, CCL4, TNF, IL1B, S100A12) were expressed at higher levels in brucellosis patients than in healthy donors." (PMID 39135683, 2024).